CD4 (CD4 molecule)
Diseases named in the same sentence as CD4 in open-access papers (continued):
Sharing a sentence is not in itself a finding about the gene and the disease.
tumor (continued). "In a previous study, LC-MSCs reduced the number of CD4+ T cells producing IL-17 and cytotoxic CD8+ T lymphocytes (CTLs) and suppressed the expression of cytotoxic molecules (Fas ligand (FasL), perforin (PFP) and CD107) in CTLs that mediate anti-tumor immune responses." (PMID 35842634, 2022). "Through analyzing whether ZNF320 expression was associated to immune infiltration levels in HCC, we discovered a positive correlation between ZNF320 expression and tumor purity, infiltrating levels of B cells, CD8+ T cells, CD4 + T cells, Macrophage, Neutrophils, and Dendritic cell." (PMID 36287187, 2022). "Moreover, the combined treatment with anti-PD-1 and DIM could increase the percentage of CD4+ and CD8+ T cells in spleen, blood and tumor tissue compared with the single treatment group." (PMID 35773674, 2022). "Although monoallelic deficiency of LIS1 did not detectably affect CD4+ T-cell proliferation in vitro, the partial loss of LIS1 function may enhance the risk of aneuploidy-driven cancer in a tumor-suppressor-failing context." (PMID 36519536, 2022). "Besides, they implied that CD4+ T cells do not play a noticeable role in the antibody-induced tumor regression." (PMID 35392976, 2022). "Thus, density numbers of infiltrating CD8+, CD4+, and FOXP3+ T-cell lymphocytes, CD20+ T-cell lymphocytes, and CD68+ and CD163+ macrophages were separately evaluated in both the tumor nests and surrounding stroma, and the mean numbers were correlated with the mean values for NLR, PLR, SII and LMR." (PMID 35958590, 2022). "We believe that CD3, CD4, CD5, and CD8 may contribute to PD-1-mediated tumor control." (PMID 36514573, 2022). "Notably, recent studies have reported that, in addition to CD4+ Tregs, CD8+ Tregs could have prominent roles in tumor immune evasion." (PMID 35804964, 2022). "Tumors with a high RvD score evidenced increased CD4+ and CD8+ T cell infiltration, key for anti-tumor immunity in HNSC, but also decreased levels of anti-tumoral effectors such as plasma and dendritic cells, even if a specific subpopulation of these cells may also have a pro-tumorigenic role." (PMID 35742918, 2022). "Moreover, tBregs can also directly activate the regulatory functions of MDSCs-derived monocytes and granulocyte subsets, while activated MDSCs have been shown to improve production of ROS and NO, and more effectively inhibit CD4+ T and CD8+ T cells, thereby promoting tumor metastasis." (PMID 36158661, 2022). "We investigated the association of FNDC5 with various immune cells in the tumor microenvironment and found a significant negative correlation between FNDC5 and CD4+ memory T cells, implying an increase in the number of CD4+ memory T cells when FNDC5 was lowly expressed." (PMID 36386179, 2022). "Furthermore, CIK therapy plus anti-PD-1 treatment was shown to be a feasible combination therapy method to promote the anti-tumor response of CIK cells and inhibit tumor progression, especially for NSCLC patients with dysfunctional and low proportion of CD4+ T cells in their peripheral blood." (PMID 35523765, 2022). "Therefore, it is tempting to speculate that the increased expression of CD69 and PD-1 on both CD4 effectors and CD8 T cells resulted from yet undefined soluble factors released by tumor cells." (PMID 36458012, 2022). "There were also changes in minor subpopulations of leukocytes in tumour-bearing animals not obvious in the compositional data due to their small numbers; these included changes to CD4 T regulatory cells, DC, macrophages and PD-L1-expressing myeloid cell populations." (PMID 35226704, 2022). "In tumor-bearing immunocompetent mice, NK cells may promote the development of a cytotoxic immune response, independent of CD4+ T lymphocytes, as the depletion of CD8+ T lymphocytes promoted the onset of lung metastases." (PMID 36294305, 2022).
tumor (continued). "To verify these results, we established a syngeneic tumor model, which revealed that the SGLT2 inhibitor or SGLT2 silencing both significantly inhibited the tumor growth and significantly increased the number of infiltrated immune cells, including CD4+ and CD8+ lymphocyte cells." (PMID 35662245, 2022). "In addition, patients with longer survival had higher frequencies of tumor-infiltrating non-proliferating (Ki-67−) conventional and regulatory (Foxp3+) CD4 T cells and lower frequencies of infiltrating proliferating (Ki-67+) CD4 T cells." (PMID 35662283, 2022). "Furthermore, a strong positive correlation was observed between frequencies of FoxP3+Helios+ T cells and CD4+PD-1+ T cells in NILs in CRC patients, and it was found to be stronger in early tumor stages compared to advanced stages (r = 0.818, p = 0.005 [early]; r = 0.393, p = 0.206 [advanced])." (PMID 36146549, 2022). "We also noticed a majority of NK+ cells, CD4+ and other non-T cells at the tumour site." (PMID 35057046, 2022). "Furthermore, prostaglandin E derived from tumor-activated Schwann cells blocked the proliferation of CD3/CD28-activated T cells and upregulated the expression of CD73 and PD-1 on both CD4+ and CD8+ T cells, suggesting T cell polarization to the exhausted phenotype." (PMID 36428970, 2022). "Besides, the administration of αVISTA (VISTA mAb) shows similar anti-tumor effect in the B16OVA melanoma model, where the count of CD4+ T cells and CD8+ T cells increased (6.38% to 11.74%, 9.25% to 17.74%, respectively), and the percentage of MDSCs significantly decreased (37.74% to 25.64)." (PMID 35831836, 2022). "Assessment of tumor CD8+ and CD4+ T-cell percentages using flow cytometry revealed a trend toward a higher CD8+ T-cell percentage, a significantly lower CD4+ T-cell percentages (P=0.0004) and a higher CD8+:CD4+ T-cell ratio (P = 0.004) in the combination arm than in the nivolumab-alone arm." (PMID 36212401, 2022). "Additionally, CD8+ T cells are not the only lymphocyte population involved in tumor immunity, and CD4+ T cells are known to be required in many tumor models." (PMID 35267487, 2022). "Infiltration of type 2 (CD4+ T-helper cells or Th2), including Forkhead box P3 (FOXP3) CD4+ regulatory T-cells, inhibits cytotoxic T-cells (CTL) function, supports proliferation and promotes an adaptive anti-inflammatory immune response that is responsible for tumor growth." (PMID 36003772, 2022). "Corroborating this assumption, our data show that whole platelets, as well as tumour cell-induced releasates, evoked Treg differentiation from CD3/CD28/CD2 stimulated CD4+ T cells, although further cell types than regulatory T cells might contribute to IL-10 release from PBMCs." (PMID 35285006, 2022). "However, type 2 CD4+ T-helper cells (Th2), including Forkhead box P3 (FOXP3) CD4+ regulatory T-cells, inhibit CD8+ cytotoxic T-cell function, promoting an anti-inflammatory immune response that could stimulate tumor growth." (PMID 36010863, 2022). "Manual gating validated that PD-1+GB−CD8+ exhausted T cells, Foxp3+CD152+CD4+ Treg, and PD-1+CD45RO+CD4+ memory T cells were enriched; while GB+CD56+ active NK cells and PD-1−GB+CD8+ activated T cells were depleted, specifically in S2 tumours compared to S1 or S3 tumours or both." (PMID 35301339, 2022). "Moreover, ICI analysis further indicated that HIF-1α was positively correlated with multiple immune cells, especially with CD4+, CD8+, and γΔ T cells, and the corresponding phenomenon was also validated in tumor tissues with high-throughput sequencing and immunofluorescence staining experiments." (PMID 36091021, 2022). "On the other hand, CD4 + T-helper 2 (Th2) cells, including Foxp3+ Treg cells, inhibit CTL function, support B lymphocyte proliferation, and may promote anti-inflammatory immune response, thereby promoting tumor growth." (PMID 35242718, 2022). "CD4+ T regulatory cells, MDSC and mast cells may promote tumor progression." (PMID 36171881, 2022).
tumor (continued). "Moreover, CD8+ but not CD4+ T-cell tumor infiltration as revealed by IHC correlated significantly with clonality of the TIL repertoire, highlighting the dominance of CD8+ T-cell clonal expansion in the ccRCC TME." (PMID 36185254, 2022). "The absence of abnormal growth of transplanted CD4+ T cells with the CARD11 mutation and the lack of tumor development in recipient mice provide confirmation that CARD11(E626K)CD4-Cre mice developed inflammation rather than neoplasia." (PMID 36446869, 2022). "Tumor microenvironment analysis showed that FUBP3 may be connected to immune infiltration, and immunohistochemistry identified a positive correlation between immune cells (CD4 + T cells, CD8 + T cells, and macrophages) and FUBP3." (PMID 35413821, 2022). "QA-based ISCOMATRIX vaccines could increase CD4+ and CD8+ T cells and elicit an anti-tumor effect." (PMID 36015215, 2022). "Additionally, CD4-IL15/IL15sushi CAR cells outperformed CD4 CAR cells in vivo, reducing tumor burden and providing survival benefit, suggesting that the secreted IL15/IL15sushi complex may be beneficial in the treatment of T-cell malignancies." (PMID 36172388, 2022). "Importantly, flow cytometry analysis of the tumors obtained after WNK463 therapy (left) revealed a dose-dependent decrease in PD-L1 levels in neoplastic cell populations but an increase in IFN-γ and TNF-α produced by CD4+ and CD8+ T cells in tumor-infiltrating lymphocytes." (PMID 36357569, 2022). "While most previous studies used tumor-transformed cell lines as infection models and/or pseudotyped HIV-1 particles, we decided to determine how genuine HIV-1 strains, including primary transmitted-founder HIV-1 infectious molecular clones (IMCs), impact CD155 expression on primary CD4+ T cells." (PMID 35749424, 2022). "In addition to the lymphoid lineage markers including CD3, CD4, CD8, CD20, CD45, CD56, and FOXP3, we also examined myeloid lineage markers such as CD14, CD68, CD34 to accurately identify the specific cell types within the tumor microenvironment of YTMA-76." (PMID 35810563, 2022). "Supporting the view that CD4+ T‐helper cell infiltration might be an indicator of protumor response, is also the current finding that intra‐epithelial CD4+ infiltration at the ITF correlated with advanced tumor stage and poor differentiation." (PMID 36177667, 2022). "DCs traffic between the tumor and lymph node, phagocytosing tumor cell debris and presenting peptide antigens, which are displayed on MHC-I (major histocompatibility complex class I) and MHC-II molecules, to T cell receptors (TCRs) on naïve CD8+ and CD4+ T cells, respectively." (PMID 36382146, 2022). "Notably, cell types expressing PD-1 included CD8+ T-cells, CD4+ T-cells, T-regs, and CD20+ B-cells, supporting the notion that multiple cellular subtypes may be involved in tumor response to ICIs." (PMID 35743435, 2022). "However, DPP inhibitors also promoted the recruitment of tumor-infiltrating CD45, MPO, F4/80, CD4, Foxp3-positive cells, and MDSC and decreased CD8-positive lymphocytes in metastatic sites in mouse breast cancer models by ROS-NF-κB-dependent NLRP3 inflammasome activation." (PMID 35739593, 2022). "Furthermore, the Gal9 expressed by CD4+CD25+ Tregs could contribute to the development of M2 macrophages and lead to an increasingly suppressive anti-tumor CD8+ T cell response and inflammatory conditions." (PMID 35433427, 2022). "Previous reports have pointed out that activated CD4 T cells have the ability to inhibit tumor, it could not only directly produce toxic effects on tumor cells, but also play an auxiliary role in the activation and proliferation of CD8 T cells." (PMID 35126478, 2022). "Tumor ROIs that expressed high levels of CD20 in long-term survival showed a high expression of various T cell markers like CD3, CD4 and CD8 and of HLADR marker that might be expressed by memory B cells or dendritic cells (DCs) or antigen-presenting cells (APCs)." (PMID 36685537, 2022).
tumor (continued). "In addition, the combination treatment also affected the anti-tumor immune response in other organs, as observed by a rise of the CD8+ and CD4+ T cells in the spleen, increasing the secretion of pro-inflammatory cytokine IL-12, and decreasing the secretion of pro-tumor inflammatory factor IL-6." (PMID 36329529, 2022). "Using Vectra Polaris imaging platform to quantify cell densities within whole tumor sections (one patient’s tissue section failed to collect data due to quality issues), we determined the average intratumor densities of PD-L1, PD-1, CD4, CD8, and CD56 positive cells." (PMID 35311077, 2022). "However, the adoptive transfer of OTII CD4+ T cells failed to inhibit tumor progression when they expressed SULT2B1b." (PMID 35094065, 2022). "However, the tumor size and tumor-induced lethality were similar between the recipients of WT OT-II cells and KO OT-II cells, indicating that SENP7 is dispensable for CD4+ T cell antitumor function." (PMID 35143421, 2022). "Analyzing the phenotypical characteristics of CD4+ T cells infiltrating tumor and normal tissue, it was found that independent of the pathologic response, there was an increase in the frequency of Tregs, characterized by expression of the IL-2 receptor α chain (CD25) and FoxP3 transcription factor." (PMID 35562400, 2022). "The clustering of T/NK cells of the tumor environment revealed 5 main populations, including NK/NKT subtype (GNLY and TRDC), γδ T cells (GNLY, TRDC, and CD3D), CD4+CD8+ T cell subtype (CD3D, CD8A, and CD4), CD8+ T cells (CD3D and CD8A), and CD4+ T cells (CD3D and CD4)." (PMID 35907904, 2022). "Additionally, KCC2 positively correlated with the levels of tumor-infiltrating macrophages and CD4+ T cells, but NKCC1 showed a significantly widely negative association with tumor-infiltrated lymphocytes, suggesting an immune-excluded TME in cancers." (PMID 35372048, 2022). "Cationic liposomes loaded with tumor-specific synthetic long peptides (SLPs) and TLR3 ligands as adjuvants could also induce cytotoxicity against target cells in vivo by strongly activating functional antigen-specific CD4+ T cells and CD8+ T cells." (PMID 35413927, 2022). "In tumours that are abundant in tumour-infiltrating FoxP3high, CD45RA−, CD4+ T cells [effector Treg (eTreg) cells], PD-1 blockade may actually facilitate the proliferation of these highly suppressive PD-1+ eTreg cells, resulting in further inhibition of pre-existing antitumor immunity." (PMID 35393508, 2022). "Thus, it is not suitable to use IFN-γ to represent the anti-tumor activities of TGFβ/IFNγ-producing CD4 T cells." (PMID 36289759, 2022). "Upon the addition of ICM, we propose that the tumor-specific CD8+ T cells no longer required assistance from CD4+ T cells and NK cells to mediate the antitumor effect and that ICM was providing (or blocking) the signals to CD8+ T cells required to promote an optimal effector response." (PMID 35857851, 2022). "The presence of ENTPD1/CD39 in multiple cell types other than certain cancers (e.g., CD4 + / Treg, CD8 + and MDSC) supports the consideration of therapeutic assessment of combined ENTPD1/CD39 inhibition and Vigil in patients with ENTPD1/CD39high tumor expression." (PMID 36051466, 2022). "Also, in areas with no visible tumor proliferation, the frequency of Tregs among CD4 T-cells and the density of Tregs increased compared with healthy mice." (PMID 34584204, 2022). "Thus, in this model, the anti-tumour activity of anti-mCD27 is dependent on appropriate FcγR interaction, with engagement of activatory FcγR detrimental to therapy, likely as a result of depletion of CD8+ and effector CD4+ T cells." (PMID 35288635, 2022). "In addition, significantly reduced infiltration of CD4+ T cells, CD8+ T cells, and NK cells may trigger tumor immune evasion and ultimately lead to the progression, high recurrence, and poor prognosis of HCC based on their functions." (PMID 36263042, 2022).
tumor (continued). "Also, T cell activation was enhanced, and the levels of TILs were significantly increased, the anti-tumor function of CD8+T cells and CD4+Th1 cells were enhanced, and supported the transition of CD8+T cells to long-term memory cells, while the levels of Treg cells were reduced." (PMID 35897036, 2022). "Analysis of infiltrated immune cells demonstrated that the USP8 inhibitor combined with anti-PD-L1 treatment could significantly increase the percentage of CD8+ T cells, but not the CD4+ cells in tumor-infiltrating lymphocytes (TILs)." (PMID 35361799, 2022). "MHC class II expression is found predominantly on myeloid cells, B cells, DCs, and activated CD4+ and CD8+ T cells; however, in some cases tumor cells express MHC class II, which raises the question of whether DP CD4+ Th TILs can recognize their cognate antigen directly in the TME." (PMID 35439168, 2022). "Studies on tumor-bearing mouse models have demonstrated that multi-targeted anti-angiogenic tyrosine kinase inhibitors (TKIs) increased tumor infiltration of CD8+ and CD4+ T cells by downregulating PD-1 expression, and decreased the number and activity of Tregs and MDSCs." (PMID 35281003, 2022). "We found SCT treatment markedly increased CD4+ T cell, B cell, and NKT cell fractions in spleens, NKT cells in lymph nodes, as well as increased Th1 and Th17, as well as granzyme B+, perforin+, and IFN‐γ+ CD8+ effector T cell populations in the tumor‐infiltrating T cells." (PMID 34747157, 2022). "Finally, our results show that tumor-reactive CD4+ and CD8+ T cells recognized distinct epitopes, suggesting that CD4+ and CD8+ T cells might play a complementary role in the antitumor response." (PMID 35439168, 2022). "However, this is not the main anti-tumor effect enacted by CD4+ T-cells but a more assistive role observed via the activation of immune effector pathways that stimulates cytokine production and other aspects of the innate immune system." (PMID 35890342, 2022). "However, activated tumor-specific CD4+ T cells can restrain the metastatic foci, no matter macrophages are present or not, indicating that activated CD4+ T cells play a dominant role in tumor control in this model." (PMID 35784297, 2022). "While anti-tumor activity in cancers lacking both HLA-II and HLA-I expression is thought to be coordinated by NK and CD4+ T cells, we propose that the distinct expression of HLA-II on NSCLC cells presents a viable pathway for cytotoxic CD4+ T cells to drive ICB response in HLA-I-disrupted patients." (PMID 35831288, 2022). "CD4+T cells and macrophages were found negative and complex in tumor immunity, respectively." (PMID 36274838, 2022). "Much research has reported that high infiltration of immune cells, especially adaptive immune cells like activated CD4+ T cells and CD8+ T cells, could effectively promote the ability of the immune system of eliminating tumor cells, thereby inhibiting tumor growth." (PMID 36035178, 2022). "Moreover, a drop in CD8 T cells but not in CD4 T cells is observed when CCL5-treated tumor cells are co-cultured with peripheral blood mononuclear cells (PBMCs)." (PMID 36429101, 2022). "To investigate whether the reduced tumor growth in GPR182−/− mice was due to improved antitumor T cell response, we depleted CD4+ and CD8+ T cells in GPR182−/− and WT mice by intraperitoneal injection of anti-CD4 and anti-CD8β depleting mAbs together." (PMID 35013216, 2022). "So, because of this complexity in CD4+TILs function in tumor area, it can be conferred that these cells could not be a good predictor of prognosis." (PMID 36319566, 2022). "By day twenty post tumor inoculation, tumor-bearing mice experienced significant increases in the presence of tumor-associated macrophages and trends toward (but not statistically significant) decreases in proportions of effector NK1.1+ cells and CD8+:CD4+ T cell ratios." (PMID 35406547, 2022).